KRTAP13-1 (keratin associated protein 13-1)
Description:
In the hair cortex, hair keratin intermediate filaments are embedded in an interfilamentous matrix, consisting of hair keratin-associated proteins (KRTAP), which are essential for the formation of a rigid and resistant hair shaft through their extensive disulfide bond cross-linking with abundant cysteine residues of hair keratins. The matrix proteins include the high-sulfur and high-glycine-tyrosine keratins.
Synonyms: KAP13.1; KRTAP13.1
Tractability: No criterion of Open Targets' tractability assessment is met for any kind of drug.
Gene: Protein-coding gene on chromosome 21 (30,396,031 to 30,396,822, forward strand). Ensembl gene ENSG00000198390.
Pathways (Reactome):
Developmental Biology: Keratinization
Gene Ontology:
Molecular function: structural molecule activity
Cellular component: cytosol; keratin filament
Genetic constraint (gnomAD): Loss-of-function variants: 1 observed, 1.09 expected, observed/expected ratio (o/e) 0.92, 90% interval 0.25 to 1.88. That is too few expected variants to judge how well the gene tolerates losing a copy. Missense variants: 200 observed, 211.7 expected, observed/expected ratio (o/e) 0.94, 90% interval 0.84 to 1.06. Synonymous variants: 104 observed, 88.3 expected, observed/expected ratio (o/e) 1.18, 90% interval 1 to 1.39.
Homologues: Orthologues: chimpanzee KRTAP13-1 (99% identical), rat Krtap13-1 (65% identical), mouse Krtap13-1 (63% identical), rabbit KRTAP13-4 (63% identical). Paralogues in human: KRTAP13-2 (91% identical), KRTAP13-4 (72% identical), KRTAP13-3 (69% identical), KRTAP15-1 (47% identical), KRTAP11-1 (38% identical), KRTAP26-1 (28% identical), KRTAP27-1 (26% identical), KRTAP25-1 (19% identical).